KLF9 (KLF transcription factor 9)
Diseases named in the same sentence as KLF9 in open-access papers (continued):
Sharing a sentence is not in itself a finding about the gene and the disease.
tumor (continued). "In luminal ER + MCF7 cells, KLF9 cooperated with GC to effect tumor suppression, whereas KLF9 restrained the GC-induced oncogenic effects in triple-negative MCF10A and MDA-MB-231 cells." (PMID 36823570, 2023). "Low nuclear expression of KLF9 via IHC staining was observed in 62% of PDAC tumor tissues, compared to high expression in only 38% of tumors." (PMID 37239940, 2023). "Despite mounting evidence implicating KLF9 as a tumor suppressor, its role in the emerging link between hormone signaling, circadian disruption, and BCa development is yet to be explored." (PMID 36823570, 2023). "The tumor-associated increase in KLF9 expression was ascribed to KLF9′s stimulation of LINC00664 gene activity, which has been previously shown to promote tumor growth in vitro and in vivo." (PMID 38067370, 2023). "Our findings further enrich the complicated connection between the KLFs and cancer by establishing a tumour‐suppressive role of KLF9 in HCC progression." (PMID 37400979, 2023). "KLF9 induces the arrest of cancer cells in the G2/M phase in PC and blocks the cell cycle in the S phase in lung adenocarcinoma, thereby inhibiting tumor growth." (PMID 36761967, 2023). "Consistent with its role in cell growth in vitro, altered expression of KLF9 only mildly affects the tumour growth of metastatic liver cancer cells in vivo." (PMID 37400979, 2023). "Thus, the loss of circadian oscillation of KLF9 in MDA-MB-231 cells may not only be a consequence of dysregulated rhythms in BCa but may also actively influence tumor progression depending on the transcriptional program orchestrated by KLF9 downstream of its rhythmic expression." (PMID 36823570, 2023). "Stratifying tumor samples into molecular subtypes based on transcriptomic data from TCGA and SCAN-B, expression of KLF9 was moderately downregulated in subtypes associated with increasing disease severity and worse prognosis." (PMID 36823570, 2023). "KLF9 is a suppressor of oxidative stress and inflammation in the livers of high fat-fed mice, effects that are predicted to be tumor-preventive." (PMID 38067370, 2023). "Some of the ways to get at this question include Chip-Seq, single cell RNA-seq, and single cell proteomics studies for multiple normal and tumor cell types and tissues simultaneously for both KLF9 and KLF13." (PMID 38067370, 2023). "We also highlight the great diversity of miRNAs, lncRNAs, and circular RNAs which provide mechanisms for the ubiquitous tumor-specific suppression of KLF9 mRNA and protein." (PMID 38067370, 2023). "The expression patterns of PLK1 and CDKN2A were considerably up-modulated in most tumour types, while KLF9 was the opposite." (PMID 36186436, 2022). "KLF9 modulation of oxidative stress-induced cell death in the lung, combined with its putative tumor-suppressive role in the liver, suggested further functional consideration within the physiological context of hepatic and systemic oxidative stress." (PMID 35406507, 2022). "KLF9 appeared to be a cancer suppressor gene in our investigation, as it was downregulated threefold in tumor tissues; yet, it also contributed to patient survival shortening since it was enriched in the high-risk group." (PMID 36186479, 2022). "In vivo findings revealed that silencing KLF9 induced tumor growth by enhancing MDSC-mediated immunosuppression through upregulation of GADD34." (PMID 35501353, 2022). "Loss of KLF9 leads to the inhibition of PGR and FOXO signaling, hence leading to oncogenesis and tumor invasion in endometrial cells." (PMID 35047407, 2021). "As reported, KLF9 elevated intracellular ROS level by reducing the expressions of the reductases, resulting in its impacts on tumor cell proliferation, apoptosis, and metastasis." (PMID 34120140, 2021).
tumor (continued). "In the case of KLF9, its expression was much more significantly reduced in the advanced tumor stage and distant metastatic groups relative to its less reduced expression in the lower tumor stage and non-metastatic groups." (PMID 35047407, 2021). "Although a direct mechanistic link between EC pathogenesis and KLF9 loss of expression has yet to be evaluated, our findings are consistent with the increasing validation of KLF9 tumor-suppressive functions in mouse models of cancer and in cancer cell lines." (PMID 32046384, 2020). "By contrast, we found that MET modified the nuclear levels of immunoreactive ERα, PGR, and KLF9 proteins in tumor tissues and preferentially affected GE relative to ST." (PMID 32046384, 2020). "Given its tumor-suppressor role as inhibitor of the miR-636/KLF9 interaction, circPTPRA emerges as a potential novel prognostic biomarker and therapeutic target for BC." (PMID 31821171, 2019). "MTS assays indicated similar loss in cell viability in KLF9-expressing GSCs when treated with SAHA or TSA, suggesting a universal tumor cell killing effect of KLF9 in conjunction with HDAC inhibitors." (PMID 30348136, 2018). "We then examined tumor cell death when forced KLF9 expression was combined with a variety of anti-tumor reagents, including chemotherapeutic drugs and epigenetic modulators." (PMID 30348136, 2018). "In this study, we investigated the cell death responses of GSCs to KLF9 expression alone and in conjunction with other anti-tumor reagents." (PMID 30348136, 2018). "Dox at 0.1–1 μg/ml induced ~ 10–15 fold KLF9 expression, which was found to reduce stem cell marker expression and decrease tumor-propagating capacity of GSCs as we previously reported." (PMID 30348136, 2018). "This would be consistent with reports that Klf9 can act as a tumor suppressor and promote apoptosis in response to chemotherapeutics." (PMID 28407733, 2017). "In this tumor type, downstream repression of regulators of the actin cytoskeleton has been detected by microarray in modified cell lines overexpressing KLF9." (PMID 25593984, 2014). "The nature of the participants in this network implicates KLF9 in control of endometrial cell adhesion to substratum, tumor cell migration and invasion, cell stress responses, embryo attachment to endometrium, and uterine remodeling." (PMID 18783612, 2008). "In this respect, the combination of KLF9 inhibitors and conventional chemotherapy drugs may improve the sensitivity of cancer cells to treatment, especially in malignancies where KLF9 promotes tumor survival and proliferation." (PMID 40860800, 2025). "Interestingly, KLF9 was upregulated in primary OC tissues, and its lentivirus-mediated knockdown inhibited cell proliferation, induced G0/G1 arrest, and reduced tumor growth in xenografts." (PMID 40860800, 2025). "Importantly, we reveal a novel WTAP–KLF9 regulatory axis, in which WTAP positively modulates the expression of the tumor suppressor gene KLF9, thereby contributing to its anti-tumor function." (PMID 41301778, 2025). "Protein-protein interaction analysis revealed SAE1 could suppress KLF9 alongside other tumor suppressors while activating oncogenic pathways." (PMID 40860800, 2025). "For instance, compounds that augment KLF9 activity could be therapeutically advantageous in conditions characterized by its downregulation, such as certain cancers where KLF9 functions as a tumor suppressor." (PMID 40860800, 2025). "Accordingly, modulation of selective ncRNA-KLF9 interactions could enable targeted restoration of KLF9-driven tumor suppression while circumventing inherent genetic or epigenetic constraints." (PMID 40860800, 2025). "KLF9, as a transcription factor, plays an important role in regulating tumor cell apoptosis." (PMID 40860800, 2025).
tumor (continued). "Accordingly, understanding the regulatory landscape of KLF9 in CAFs is crucial for developing strategies aimed at restoring its expression or function, potentially reversing the pro-tumorigenic effects of CAFs in the tumor microenvironment." (PMID 40860800, 2025). "Therefore, while the current data support a WTAP–KLF9 regulatory link, we cannot exclude the possibility that KLF9 also exerts separate tumor-suppressive functions." (PMID 41301778, 2025). "Besides, KLF9 exhibits pan-subtype tumor-suppressive activity, while demonstrating context-dependent therapeutic modulation." (PMID 40860800, 2025). "Future research should prioritize mapping KLF9’s spatiotemporal dynamics within tumor microenvironments and elucidating its interplay with hypoxic stress, insights critical for developing precision vascular normalization strategies to impede cancer progression." (PMID 40860800, 2025). "Moreover, the study revealed that high expression of PLK1 had a poor prognosis in 11 tumor types, including KIRC, KIRP, etc., while high expression of KLF9 was associated with a better prognosis in KIRC." (PMID 37000317, 2023). "Moreover, our cellular assays demonstrate that KLF9 generally functions as a tumor suppressor in mammary epithelial cells by inhibiting neoplastic transformation, reducing proliferation, enhancing DOX-induced apoptosis, and restricting migration (#5)." (PMID 36823570, 2023). "It showed that KLF9 could induce apoptosis, block the cell cycle at the S phase, and inhibit the migration and invasion of tumor cells." (PMID 37239940, 2023). "Characterization of the role of KLF9 using complementary cancer hallmark assays in the context of the hormone-circadian axis revealed that KLF9 plays a tumor-suppressive role in BCa regardless of molecular subtype." (PMID 36823570, 2023). "However, other studies highlighted the importance of KLF9-dependent upregulation of ROS in controlling tumor progression via oxidative stress." (PMID 37111314, 2023). "Several previous studies have revealed that KLF9 could regulate tumour initiation in other cancer types, in concert with our perspective that KLF9 works as an EMT regulator." (PMID 37400979, 2023). "Conversely, KLF9 was significantly overexpressed in normal samples compared to tumor samples." (PMID 37000317, 2023). "Anti-miRs with therapeutic efficacy and tumor-specificity could be designed to selectively enhance KLF9 protein translation in tumors, as, for example, in antibody-drug conjugates." (PMID 38067370, 2023). "This is a tissue example of the putative tumor-promoting effects of KLF9." (PMID 38067370, 2023). "Further, the co-expression of KLF9 and KLF13 transcripts is evident in the tumor-associated immune cells (e.g., B cells, mast cells, myeloid cells, and T cells), whereas KLF13 mRNA predominates in the tumor-associated plasma cells." (PMID 38067370, 2023). "The expression of KLF9 and KLF13 in tumor-associated immune cells and tumor stroma, coupled with the known biology of these proteins in circulating immune cells, makes a strong case for focusing on the functions of these two KLFs in the tumor microenvironment of solid tumors and blood cancers." (PMID 38067370, 2023). "KLF9 gene expression is markedly lower in NSCLC tumors than matched adjacent normal lung tissue, which may be partly due to oncogenic miR-570 targeting of the 3′-UTR of KLF9 mRNA, as shown in tumor cell lines." (PMID 38067370, 2023). "KLF9 is over-expressed in human OSCC tumor tissue compared with adjacent normal tissue." (PMID 38067370, 2023). "In fact, this exciting relationship between KLF9's function and the status of essential oncogenes or tumour suppressors is reminiscent of the findings of KLF5, suggesting that this could be, to some level, a common phenomenon of the KLF family." (PMID 37400979, 2023). "Moreover, previous studies have suggested that KLF9 is a tumor suppressor involved in development of EC." (PMID 35830453, 2022).
tumor (continued). "To determine whether miR-300/KLF9 axis was involved in Mxi1-suppressed tumor growth, we modulated the expression of Mxi1, miR-300, and KLF9 separately or in combination." (PMID 35501353, 2022). "The data identify a role for KLF9 in reducing hepatic and systemic oxidative stress and hepatic inflammatory state, independent of overt effects on adiposity, and provide potential mechanisms for tumor suppression within the hepatobiliary system." (PMID 35406507, 2022). "Previous studies demonstrated that miR-889 could regulate the tumor cellular behaviors by targeting serval target genes, such as KLF9, SIX1, DAB2IP, TAB1, FGFR2, TWEAK." (PMID 34116691, 2021). "Furthermore, in the case of KLF9, we observed its reduced expression in advanced tumor stage (0.01 ± 1.6) and in distant metastasis (0.007 ± 1.39)." (PMID 35047407, 2021). "Moreover, KLF9 is an upstream positive regulator of miR-483-3p and also functions as a tumor suppressor in SEM." (PMID 33659208, 2020). "Overall, KLF9 might function as a tumor suppressor via positively regulating the expression of miR-483-3p." (PMID 33659208, 2020). "Therefore, our study has validated that miR-483-3p, mediated by KLF9, is a tumor suppressor in testicular SEM." (PMID 33659208, 2020). "Subsequently, CCK-8 and cell colony formation assays revealed that KLF9 was a tumor suppressor which could inhibit the growth of TCam-2 cells." (PMID 33659208, 2020). "Moreover, KLF9 was identified as a potential upstream regulator of miR-483-3p and functions as a tumor suppressor." (PMID 33659208, 2020). "Moreover, IHC analysis indicated that overexpression of circPTPRA was correlated with upregulation of KLF9 in tumor samples." (PMID 31821171, 2019). "KLF9 is reported to be oncogenic in some contexts and to be tumor suppressive in others." (PMID 30250042, 2018). "Furthermore, KLF9 was shown to function as a suppressor of tumor-initiating stem cells by directly suppressing Notch1 signaling." (PMID 25880754, 2015). "Furthermore, the outcome of m6A modification is known to depend on the relative activity of m6A “readers” and “erasers,” suggesting that WTAP might preferentially enhance m6A modification on transcripts such as KLF9 that contribute to tumor inhibition." (PMID 41301778, 2025). "For instance, KLF9 has been implicated in the downregulation of integrins such as ITGA6 and ITGB1, which are crucial for cell adhesion and migration, suggesting that KLF9 may inhibit the invasive potential of CAFs, thereby limiting their ability to promote tumor metastasis." (PMID 40860800, 2025). "In addition, the expression level of KLF9 may be influenced by multiple factors such as the tumor microenvironment and the physiological status of patients, further complicating its application as a clinical biomarker." (PMID 40860800, 2025). "However, in contrast to other tumors, KLF9 plays a role in NPC that promotes tumor progression." (PMID 37644041, 2023). "IL-6 may facilitate tumor metastasis via induction of glutathione release from hepatocytes and inter-organ transfer to metastatic foci, providing an experimentally testable connection between KLF9, IL-6, glutathione, and cancer dissemination in future studies." (PMID 35406507, 2022). "Repression of glycolytic genes by Klf9 fits with its reported inhibition of growth and regeneration and regulation of stem-cell metabolism and could also contribute to its role in tumor suppression, given the reliance of cancer cells on glycolysis." (PMID 34692682, 2021). "We also evaluated the association between DNA methylation and mRNA expression of KLFs in PCa tumour tissues and found that the mRNA expression of most KLFs was negatively associated with its DNA methylation at the promoter region (P < .05), except for KLF3, KLF9 and KLF17." (PMID 32281273, 2020).
tumor (continued). "By siRNA targeting of KLF9 in Ishikawa cells to mimic the low levels found in EC tumors, we found that MET may compensate for the progressive loss of KLF9 in tumor cells by rapidly increasing transcript levels for PGR, PGR-B, and KLF4, all of which exhibit anti-tumor properties." (PMID 32046384, 2020). "Although mechanistic details of KLF9’s role remain unexplored in this context, its inclusion in SAE1-regulated tumor suppression networks suggests potential involvement in SAE1-driven HCC progression and metastasis." (PMID 40860800, 2025). "Among the tumor tissues of 50 CRC patients, 86% of the samples exhibited lower KLF9 expression compared to normal tissues." (PMID 40860800, 2025). "This induces acetaldehyde metabolic dysfunction and drives tumor metabolic reprogramming, with SAE1-mediated KLF9 inhibition correlating positively with poor prognosis and metastatic risk in HCC patients." (PMID 40860800, 2025). "On the other hand, among the tumor-specific 63 ceRNAs, GALNT7, KLF9, and DAB2, which are common to all three tumor tissues and were significantly expressed in at least two tissues, were found in this core miRNA:ceRNA cluster." (PMID 38627780, 2024). "Mass spectrometry has identified multiple sites of post-translational modification for KLF9 and KLF13 proteins; however, we know little about the functional relevance of these sites, especially with respect to neoplasia and responses to cancer treatments." (PMID 38067370, 2023). "This work demonstrates that reduced expression of KLF9 has a detrimental effect on the growth-promoting hormone PGR, inhibiting the transcription factor FOXO and promoting Tumor development." (PMID 37833790, 2023). "Experiments conducted in parallel confirmed the actions of specific miRs, lncRNAs, and circRNAs on KLF9 or KLF13 protein abundance and consequent effects on tumor cells in vitro and in vivo." (PMID 38067370, 2023). "DANCR exhibits different biological functions in different tumor types: KLF12 mediates the promotive effect of DANCR in HCC, while KLF9 is the ultimate target of the cancer-inhibiting effect of DANCR in multiple myeloma." (PMID 36761967, 2023). "The narrative highlights the alterations (primarily reductions) in KLF9 and KLF13 steady state levels in many different cancers, and their predominant roles as suppressors or promoters of tumor cell growth and migration." (PMID 38067370, 2023). "In our study, the expression of KLF9, MCM2, INHBA, and CGREF1 was significantly correlated with TNM clinical stage and tumor differentiation, excluding tumor location, age, and sex." (PMID 37370046, 2023). "KLF9 mRNA and protein levels are significantly lower in HCC tissue than in normal non-tumor liver tissue." (PMID 38067370, 2023). "In contrast, tumor samples had lower levels of IPMK (p = 0.0010), SPATA2 (p = 0.0071), and KLF9 (p = 0.0002)." (PMID 36186479, 2022). "Tumor growth was significantly impaired in mice receiving GADD34-silenced HCC827 cells while concomitant silencing of KLF9 and GADD34 promoted the tumor growth." (PMID 35501353, 2022). "Our primary endpoints for MET outcomes in vivo were proliferation (Ki67 immunostaining) and apoptotic (TUNEL assay) status and changes in nuclear levels of tumor biomarker proteins ERα, PGR, KLF9, and PTEN." (PMID 32046384, 2020). "With advanced gene therapy technology, our prospective in vivo testing of the synergistic cell death via KLF9 and HDAC inhibitors will help in developing new anti-tumor strategies for GBM patients." (PMID 30348136, 2018). "For example, KLF family proteins have been shown to have either a tumor-promoting (KLF4, KLF6, KLF9, KLF10, KLF11, and KLF17) or a tumor-suppressing (KLF5, KLF12) role by intervening in cell signaling associated with proliferation and/or suppression." (PMID 26320172, 2015).